OR2B3 (olfactory receptor family 2 subfamily B member 3)
Description:
Odorant receptor.
Synonyms: OR6-4; OR2B3P; 6M1-1; OR6-14
Tractability: Antibody: UniProt places it where antibodies can reach, with medium confidence; UniProt predicts a signal peptide or a membrane-spanning region; its Gene Ontology location is reachable by antibodies, with medium confidence.
Gene: Protein-coding gene on chromosome 6 (29,086,208 to 29,087,313, reverse strand). Ensembl gene ENSG00000204703.
Subcellular location: Cell membrane
Pathways (Reactome):
Sensory Perception: Expression and translocation of olfactory receptors
Gene Ontology:
Molecular function: olfactory receptor activity; G protein-coupled receptor activity
Biological process: detection of chemical stimulus involved in sensory perception of smell; G protein-coupled receptor signaling pathway
Cellular component: plasma membrane; membrane
Genetic constraint (gnomAD): Missense variants: 334 observed, 390.67 expected, observed/expected ratio (o/e) 0.85, 90% interval 0.78 to 0.94. Synonymous variants: 121 observed, 141.07 expected, observed/expected ratio (o/e) 0.86, 90% interval 0.74 to 1.
Homologues: Orthologues: chimpanzee OR2B3 (98% identical), macaque OR2B3 (96% identical). Paralogues in human: OR2B2 (72% identical), OR2B6 (71% identical), OR2B11 (58% identical), OR2G3 (57% identical), OR2J2 (56% identical), OR2G2 (55% identical), OR2J1 (55% identical), OR2J3 (55% identical), OR2G6 (54% identical), OR2W3 (54% identical), OR2W1 (54% identical), OR2Y1 (54% identical), and 80 more.